SIRPA (signal regulatory protein alpha)
Diseases named in the same sentence as SIRPA in open-access papers (continued):
Sharing a sentence is not in itself a finding about the gene and the disease.
tumor (continued). "Taken together, these data demonstrate that the armed OAd-SIRPα-Fc, OAd-Siglec10-Fc and OAd-TIGIT-Fc can selectively lyse tumor cells and secrete high levels of functional fusion proteins." (PMID 38016957, 2023). "In acidic TME, benzoic amine bonds cleave and release SIRPα and anti-CD47, enhancing tumor cell phagocytic elimination." (PMID 37345176, 2023). "“Don’t eat me” axis, e.g., CD47/SIRPα and CD24/Siglec-10 between tumor cells and myeloid cells presents an exciting paradigm for using tumor-induced inhibitory pathways to escape immune surveillance." (PMID 37822933, 2023). "Through the signal regulatory protein α/cluster of differentiation 47 (SIRPα/CD47) pathway, tumour escape from phagocytic clearance of macrophage." (PMID 37974395, 2023). "For example, the monoclonal antibody KWAR23, which binds human SIRPα with high affinity and disrupts its binding to CD47, has been shown to be a promising candidate in therapy, though in combination with tumor-opsonizing monoclonal antibodies." (PMID 37999184, 2023). "Our study reveals that SIRPα enhances immunosuppression, confers HRT resistance in CRC, and thus ensures tumor progression." (PMID 37291116, 2023). "Blocking the interaction between CD47 and macrophage SIRPα increases cytosolic DNA sensing and activates the STING pathway activation that enables detection of tumor mitochondrial DNA and subsequent antigen presentation to T cells." (PMID 37822933, 2023). "The CD47/signal-regulatory protein alpha (SIRPα) pathway is a critical innate macrophage checkpoint, as CD47 expression on tumour cells limits the phagocytic function of TAMs." (PMID 38136335, 2023). "Tumor cell escape macrophage-mediated phagocytosis via increasing the CD47 expression, which recognizes signal regulatory protein-α (SIRPα, a phagocytosis inhibitory receptor)." (PMID 37380989, 2023). "The results of this study demonstrated that OAd-SIRPα-Fc, OAd-Siglec10-Fc and OAd-TIGIT-Fc were able to produce SIRPα-Fc, Siglec10-Fc and TIGIT-Fc, respectively, which effectively bound to CD47+, CD24+ and CD155+ tumor cells." (PMID 38016957, 2023). "By interacting with immune checkpoint receptors and SIRPα on immune cells, CD47 can suppress anti-tumor immunity and promote immune evasion." (PMID 38188674, 2023). "The activity of macrophages on tumor cells is controlled through the interaction of tumoral CD47 with its receptor in macrophages, signal regulatory protein a (SIRPα)." (PMID 37199012, 2023). "IMM0306 has stronger ADCC activity compared to rituximab, stronger ADCC and ADCP compared to SIRPα-Fc, very low binding activities on human RBCs to avoid potential human cell toxicities, and a higher affinity to CD20 for strong tumor cell killing." (PMID 36575242, 2023). "The binding of SIRPA to CD47 triggers inhibitory pathways in some cancers, ultimately leading to the immune escape of tumor cells." (PMID 38228050, 2023). "In this context, EVs obtained from HEK 293 cells transfected to express SIRPα can accumulate in the tumor niche, inhibiting tumor growth by enhancing the phagocytosis of CD47+ tumor cells and increasing the infiltrating Tc cells." (PMID 37175226, 2023). "It has been shown that the phagocytosis of macrophages within the tumor microenvironment can be enhanced when the binding of CD47 and SIRPα was blocked." (PMID 37049910, 2023). "Regarding the suggested interplay between the two axes CD47:SIRPα and HLA class I:LILRB1 in counteracting effective ADCP of tumor cells as demonstrated for anti-EpCAM or anti-EGFR antibodies, additional antibody combinations were studied." (PMID 37781391, 2023). "For example, blockade of the phagocytosis checkpoint SIRPA, which binds to CD47 that is upregulated on tumor cells, has been shown to enhance myeloid cell-dependent killing of Burkitt’s lymphoma through antibody-dependent cellular phagocytosis in SRG mice." (PMID 37296949, 2023).
tumor (continued). "A study found that in a syngeneic mouse model, sEVs carrying the surface membrane protein SIRPα were transported to tumor sites, disrupting the CD47-SIRPα interaction and increasing the ability of macrophages to engulf tumor cells." (PMID 38093355, 2023). "Many tumor cells overexpress CD47, the prototypical “don’t eat me” signal that inhibits phagocytosis on normal cells from signal regulatory protein alpha (SIRPα)-expressing myeloid cells." (PMID 37090720, 2023). "Exosomes secreted from immune cells including DCs, macrophages and CD8+ T cells express SIRPα, PD1, or tumor antigen peptides, which can be used as immune modulators." (PMID 37064113, 2023). "In this study, we designed PD‐1/SIRPα fusion HAC NVs, which dual‐target the highly expressed immune checkpoint proteins PD‐L1 and CD47 on tumour cells." (PMID 37974395, 2023). "Once the anti-PD-L1 arm binds to tumor cells, the anti-CD47 arm can effectively disrupt the interaction of CD47/SIRPα and further inhibit tumor progression." (PMID 36593962, 2023). "To further explore the interaction between tumor cells (GFP labeled) and macrophages (SIRPA stained), we performed flow cytometric analysis of co-cultured cells at different time points." (PMID 36638788, 2023). "SIRPa-exosomes, acting as immune checkpoint blockade, antagonizes the crosstalk between CD47 and SIRPa, and induce tumor phagocytosis." (PMID 37064113, 2023). "IMM2902 inhibits tumor cell growth by speeding up the endocytosis and degradation of HER2 and enhances the phagocytosis of macrophages against tumor cells by blocking the interaction between CD47 and SIRPα, which acts as a “don’t eat me” signal." (PMID 36831412, 2023). "Tumor cells overexpress the “don’t eat me” signaling molecule CD47, which suppresses macrophage phagocytic capacity by interacting with signal regulatory protein alpha (SIRPa)." (PMID 36816959, 2023). "Recently, several groups reported some SIRPα mutants and CD47 antibodies showed different binding ability to CD47 on tumor cells and normal cells, indicating different glycosylation model on CD47 in malignancy and normal cells." (PMID 36593962, 2023). "CD47-targeted immunotherapy approaches aim to enhance anti-tumor immunity and improve clinical outcomes by disrupting the “don’t eat me” signal between CD47 (on cancer cells) and SIRPα (on myeloid cells)." (PMID 38188674, 2023). "To determine the effects of SIRPα on LLC cell growth in vivo, we established a mouse tumour model by s.c. injection of LLC cells in the flank of WT and KO mice." (PMID 36419386, 2023). "While checkpoint molecules such as PDL1 and SIRPα are abundantly present in M2-like TAMs, PDL1 inhibits the proliferation of anti-tumor immune subtypes, while SIRPα interacts with tumor cells, affecting their phagocytic capability." (PMID 38035101, 2023). "Anti–SIRPα alone had minimal impact on tumor proliferation, but HRT alone moderately delayed the progress of the tumor." (PMID 37291116, 2023). "Confirmation of the interplay between the CD47/SIRPα pathway and NEDD8 was substantiated by decreased deneddylation in CD68+ macrophages from tumor tissue organoids treated with anti-CD47 antibody." (PMID 36787255, 2023). "SHP1/SHP2 activity and the expression level of SIRPα were also significantly reduced in TAM-treated GH3 and AtT-20 cells as well as tumor tissues of mice." (PMID 35269804, 2022). "Tumor cells express CD47 on their surface, which can interact with SIRPα on phagocytes, resulting in phagocytosis activity of macrophages." (PMID 36678695, 2022). "The combined use of anti-SIRPα antibody and OH2 resulted in increased infiltration of CD8 T cells (p<0.01) and M1 macrophages (p<0.001) into the tumour microenvironment." (PMID 36310169, 2022). "When anti-SIRPα and OH2 were combined, they were more conducive to the infiltration of immune cells into tumour tissues, especially macrophages, DCs, T cells, and NK cells." (PMID 36310169, 2022).
tumor (continued). "IBI322 selectively binds CD47+PD-L1+ tumor cells, effectively inhibits CD47/SIRPα signaling, and instigates intense phagocytosis of CD47+PD-L1+ tumor cells by macrophages in vitro." (PMID 35978372, 2022). "Currently, different agents, such as antibodies against either CD47 or SIRPα, or other therapeutic biologics directed against CD47, are being investigated for their ability to block the CD47-SIRPα axis to promote tumor reduction." (PMID 35884427, 2022). "Currently, only PD1/PD-L1, CD47/SIRPα, TIM3/Galectin-9, and CD70/CD27 checkpoints have been shown to interact with each other to regulate tumor proliferation in pairs." (PMID 36358792, 2022). "In this review, we present the proliferative role of 15 immune checkpoints, including PD1, PD-L1, FGL1, CD155, CD47, SIRPα, CD276, IDO1, SIGLEC-15, TIM3, Galectin-9, CD70, CD27, 4-1BBL, and HVEM, in tumor progression." (PMID 36358792, 2022). "Multiple cancer cells utilize the relationship between SIRPα and its ligand CD47 to prevent tumor cell phagocytosis." (PMID 36369063, 2022). "Ligand-receptor interaction analyses indicated extensive cross-talk between the metastatic tumor cells and the MRC1+/CCL18+ macrophages; an example is the “don’t-eat-me” signaling between CD47 on tumor cells and SIRPA on the macrophages." (PMID 36376874, 2022). "Important immunological checkpoints involved in tumor immune escape include CD274, IL1B, IL1A, PDCD1, PDCD1LG2, and SIRPA." (PMID 35401746, 2022). "It was found that by blocking CD47 with anti-CD47 antibodies, the interaction between SIRPα and CD47 can be reduced, resulting in the enhancement of the ability of macrophages to present tumor cells." (PMID 36253800, 2022). "When bone marrow-derived macrophages (BMDMs) expressing the biosensor were stimulated by tumor cells that highly express CD47, researchers observed the phosphorylation of SIRPα." (PMID 35794864, 2022). "For example, lentivirus carrying sequence of signal regulatory protein alpha (SIRPα), a ligand of CD47, and plasmid inserted with PD-1 sequence were transfected into different tumor cells." (PMID 35874757, 2022). "Our results indicated that, of the selective 10 tumor-promoting genes of TAMs, only MMP19, and SIRPα can predict ICB response in ICC patients." (PMID 36158683, 2022). "Together, these existing studies have confirmed that a combined anti-CD47/SIRPα and anti-PD1/PDL1 strategy enhances the anti-tumor activity among some solid tumors." (PMID 35317832, 2022). "Tumor cells overexpress anti‐phagocytic ligands CD47, PD‐L1 MHC‐I, and CD24, and can interact with their corresponding receptors SIRPα, PD‐1, LILRB1, and Siglec‐10 on the macrophages and send “don't eat me” signals to evade phagocytic clearance by macrophages." (PMID 37323705, 2022). "By the cross priming of effector CD8+ T cells, the simultaneous delivery of SIRPα and doxorubicin, an immunogenic cell death (ICD)-inducer, achieved potent tumor growth inhibition in a melanoma model and even against tumor rechallenge in a colon cancer model." (PMID 36192487, 2022). "CD47 is a transmembrane protein with a well-described role as a “don’t eat me” signal due to its binding to signal regulatory protein α (SIRPα) on myeloid cells and high CD47 expression on tumor cells is thought to protect tumor cells from immune responses." (PMID 35720306, 2022). "The possible reason is that the density of SIRPα on the surface of exosomes was high, allowing aggregation into active clusters after binding to CD47 overexpressed on the surface of tumor cells and thereby promoting signal transduction." (PMID 35566065, 2022). "The results indicated that SIRPα-Exos presented higher CD47 affinity than control Exos, and enhanced tumor cell phagocytosis in vitro and in vivo." (PMID 36733388, 2022). "In vitro studies showed improved IgA-mediated ADCC by PMNs upon disruption of the CD47-SIRPα interaction in SKBR3 and A431 cells, either by blocking SIRPα or knocking out CD47 in the tumor cell line." (PMID 35865547, 2022).
tumor (continued). "In this study, we treated a mouse tumour model with a combination of OH2 and an anti-SIRPα antibody." (PMID 36310169, 2022). "The study showed that HX009 blocked both CD47/SIRPα and PD-1/PDL-1 interactions, and interacted with CD47 on tumor cells and PD1 on T cells to help present tumor antigens to T cells, resulting in activation of the innate and acquired immune responses." (PMID 35418166, 2022). "Macrophages harbor a membrane protein called signal regulatory protein alpha (SIRP-α) binding to CD47 molecules expressed on tumoral cells, which help them evade tumor immunosurveillance." (PMID 36303138, 2022). "Given the anti-tumor mechanisms and AEs of CD47/SIRPα blockades found in hematological malignancies’ treatment research, several points should be considered during drug design and development: 1) Can CD47 antibodies interact with RBCs?" (PMID 35978372, 2022). "The combined effect shown here on tumor growth and metastasization following the BAG3 and SIRPα blockade provides further evidence of the versatility of the anti-BAG3 tools in combination therapies." (PMID 35241649, 2022). "Signal regulatory protein alpha (SIRPα) and inhibitory receptor Ig-like transcript 2 (ILT2), which are expressed on GAMs, inhibit phagocytosis of tumor cells." (PMID 36140392, 2022). "By blocking the CD47/SIRPα axis, SIRPαD1-Fc selectively targets NSCLC cells and activated macrophages to recognize and phagocytose tumor cells." (PMID 36300110, 2022). "Meanwhile, tumor cells highly express CD47, which is the ligand of signaling regulatory protein α (SIRPα), an immune checkpoint found on macrophages." (PMID 34062992, 2021). "We further investigated the anti-tumor effects of azelnidipine in a CT26 model, which is widely used for CD47/SIRPα and TIGIT/PVR blockade therapy and the exploration of the T cell immune response." (PMID 34068552, 2021). "This Th phenotypic switch (Treg → Th1) in the post-IR Sirpα−/− TME, along with other proinflammatory elements, collectively supports an immunogenic shift that favors tumor elimination." (PMID 34050181, 2021). "Although the effect of azelnidipine for dual blocking of CD47/SIRPα and TIGIT/PVR interactions indeed occurs within one single model, it is hard to distinguish the contribution to the anti-tumor effects of either single blockade." (PMID 34068552, 2021). "Among many interactions, besides those of the integrins and signal regulatory protein α (SIRPα), CD47 binds thrombospondin-1, a potent gatekeeper of tumor progression." (PMID 34885092, 2021). "Many inhibitors have been developed to block the CD47‐SIRPα pathway and enhance tumor immunotherapy, including anti‐CD47 therapy and anti‐SIRPα therapy." (PMID 34579759, 2021). "Taking advantage of this selectivity, the two SIRPα-Fc fusion proteins achieved a biased CD47 binding selectivity, thereby facilitating phagocytosis of tumor cells while avoiding hemagglutination in patients." (PMID 33790906, 2021). "Cancer cells expressing CD47 stimulate macrophage SIRPα to generate a “don’t eat me” signal to evade phagocytosis, and the SIRPα/CD47 signaling axis is now a well-established checkpoint in tumor immunity." (PMID 34899748, 2021). "Numerous ongoing clinical trials and further clinical investigations will guide the tumor type, optimal combination therapy and timing of the therapy targeting the CD47/SIRPα axis." (PMID 34944850, 2021). "Inhibitors of CSF1R, CCL2 and CCR2, CD47/SIRPα complex antagonists, CD40 agonist antibodies, and inhibitors of PI3Kγ and TREM2 protein are undergoing clinical evaluation for various tumor types." (PMID 34638378, 2021). "Considering the fact that RT-activated Sirpα−/− macrophages possess a highly immunogenic antigen presentation capacity, we have established an in vitro system to demonstrate that Sirpα−/− macrophages may present tumor antigens to specifically activate tumoricidal Tc." (PMID 34050181, 2021).
tumor (continued). "The CD47/SIRPα and TIGIT/PVR signaling pathway jointly contribute to the immunosuppressive tumor microenvironment." (PMID 34068552, 2021). "In addition to CD47/SIRPα blockade, bispecific agents currently under investigation were designed to target either another cancer specific cell surface molecule concurrently expressed on the target tumor cells (i.e., CD19, CD20, PD-L1) or a cell surface molecule expressed by T cells (i.e., PD-1)." (PMID 34944850, 2021). "Vaccination with CD47 knockout tumor cells induces CD11c+SIRPα+ DCs activation and enhances T cell response in B16F0 melanoma mouse tumor model." (PMID 34512146, 2021). "In this preclinical study exploring RT combination strategies, we assess local tumor RT against well-established colorectal adenocarcinoma MC38 and pancreatic ductal adenocarcinoma (PDA) Pan02 and KPC in Sirpα−/− mice." (PMID 34050181, 2021). "If the tumor cells express CD47, it binds to SIRPα on phagocytic immune cells, preventing engulfment." (PMID 33802565, 2021). "We found that several pro-tumor markers are increased in cancer tissues, including CD163, CD206, SIRPα, LILRB1, SIGLEC10, AXL, MERTK, and MARCO." (PMID 34778091, 2021). "In this study, we first confirm at single-cell resolution that SIRPα is a widely expressed target within the human and mouse GBM tumor microenvironment, with a high expression observed in tumor macrophages and certain dendritic cell (DC) subsets." (PMID 34917090, 2021). "In the present study, 269 advanced CRC lesions were immunohistochemically evaluated for CD47, SIRPA, CD68, and CD163 expression in tumor cells and TAIs." (PMID 33799989, 2021). "The broken benzoic-imine bonds are cleaved to release antibodies of SIRPα and CD47 in the acidic TME abolished the “don’t eat me” signal between tumor cell and macrophages." (PMID 34062992, 2021). "By day 3 to day 6 post-IR, the infiltrating leukocytes in the Sirpα−/− TME, of which the majority were lymphocytes, already outnumbered cancer cells, which rapidly reduced as tumor size shrank." (PMID 34050181, 2021). "Three selected nanobodies binding to mouse SIRPα were radiolabeled with 99mTc, injected in GL261 tumor-bearing mice and their biodistribution was evaluated using SPECT/CT imaging and radioactivity detection in dissected organs." (PMID 34917090, 2021). "For example, the anti-SIRPα mouse antibody KWAR23 demonstrated enhanced neutrophil and macrophage anti-tumor abilities in human SIRPα knocked-in mice." (PMID 33790906, 2021). "In tumor cells, overexpressed CD47 binds signal regulatory protein alpha (SIRPα) on macrophages, resulting in inhibition of myosin accumulation, halting the subsequent phagocytosis." (PMID 33139625, 2020). "Some tumor cell targets are ligands for immune checkpoints (ICPs), such as PD-L1 and CD47, which are the interacting partner for PD-1 and SIRPα, respectively." (PMID 32370812, 2020). "Diverse therapeutics, including monoclonal antibodies to CD47 or SIRPα, receptor decoys, and bispecific antibodies that block the CD47-SIRPα axis have demonstrated significant anti-tumor activity in preclinical models of various hematological neoplasms." (PMID 32677994, 2020). "For example, blockade of CD47 promotes uptake of tumor cells by SIRPα+ cDC2, leading to activation of the cGAS-STING pathway, whereas in other tumor models it is production of 2′3′-cGAMP by tumor cells that is responsible for activation of host STING." (PMID 32508825, 2020). "First, direct inhibition of CD47 or SIRPα promotes phagocytosis of tumor cells by disrupting the “don't eat me” signal provided by CD47, allowing the engulfment of tumor cells by macrophages." (PMID 33015199, 2020). "First, tumor cells in general express CD47 molecule, an inhibitory receptor, which interacts with the signal-regulated protein alpha (SIRPα) on macrophages to prevent phagocytosis of tumor cells by macrophages." (PMID 33396603, 2020).